VAMP2 (vesicle associated membrane protein 2)
Diseases named in the same sentence as VAMP2 in open-access papers (continued):
Sharing a sentence is not in itself a finding about the gene and the disease.
neurodevelopmental disorder (10 papers, 2019 to 2025). A behavioral and cognitive disorder with onset during the developmental period that involves impaired or aberrant development of intellectual, motor, or social functions. "SYP mutations that affect VAMP2 trafficking are associated with neurodevelopmental disorders, and understanding the molecular sequence of events underlying SYP/VAMP2-mediated trafficking is vital for addressing public health concerns." (PMID 34616284, 2021).
tumor (9 papers, 2017 to 2026). "Meanwhile, enforced expression of HULC also enhanced the protein level of VAMP2 in resected tumor tissues." (PMID 34223709, 2021). "In vivo experiments implied that HULC overexpression promoted tumor growth and inhibited the chemosensitivity of Oxa through downregulating miR‐383‐5p and upregulating VAMP2." (PMID 34223709, 2021). "Our results showed that the expressionof STX1A and VAMP2 increased progressivelyaccording to the stage of the tumor." (PMID 30672978, 2019). "In tumor cells, syntaxin-4 and synaptosome-associated protein 23 (SNAP-23) serve as t-SNARE, when vesicle-associated membrane protein-2 (VAMP-2) and VAMP-8 represent v-SNARE." (PMID 31438991, 2019). "Moreover, upregulation of HULC increased the expression of HULC and VAMP2 as well as decreased the abundance of miR‐383‐5p in resected tumor tissues." (PMID 34223709, 2021). "Altogether, this analysis shows that low expression of the GABARAP family and VAMP2 correlates with a higher risk of poorer outcome in PAAD and might serve as a good indicator of poor prognosis in KRAS-G12 bearing tumours." (PMID 28581519, 2017). "VAMP2 was chosen for further analysis as most affected miR-34a target gene in the dual luciferase assay and CD11A due to its pivotal role in the anti-tumor response and T cell activation." (PMID 31311583, 2019). "In addition, previous studies have shown that VAMP2 and ZCRB1 are expressed in cancers and promote tumor progression." (PMID 41596398, 2026). "Finally, some proteins detected in tumor-derived EVs were present only in these nanoparticles and not in the corresponding tumors, and are involved in EV biogenesis, including transmembrane proteins such as CD63, synthenin-1 (SDCBP), vesicle-associated membrane protein 2 (VAMP2), and CD44A." (PMID 39337267, 2024). "VAMP2 is involved in exosome secretion via the multivesicular body (MVB) membrane fusion, and thus, it is directly involved in the preparation of premetastatic niche and CRC progression, with no direct impact on tumor chemoresistance." (PMID 39596218, 2024).
cancer (7 papers, 2019 to 2026). A tumor composed of atypical neoplastic, often pleomorphic cells that invade other tissues. "VAMP2 is an abundant synaptic vesicle protein that is closely associated with cancer cell adhesion, survival, and migration." (PMID 36248974, 2022). "Expression analysis was performed for VAMP2, and differential expression was found in cancer versus paracancer and for each clinical trait." (PMID 36248974, 2022). "Heterogenic expression of VAMP2and other SNARE proteins was found in undifferentiated colorectal carcinomas.Importantly, VAMP2 is known to be involved in the integrintrafficking and critical for cancer cell adhesion, survival, and migration." (PMID 30672978, 2019). "Additionally, VAMP2 has been shown to have a role in regulating cancer cell invasion, as knockdown of VAMP2 in HeLa cells resulted in decreased β1 integrin surface expression and cell migration." (PMID 34094984, 2021).
neurological diseases (7 papers, 2018 to 2025). "Among the relatively small number of top rated differentially regulated genes, there were at least 35 genes that have been shown to have neuron-specific functions or associated with various neurological diseases, including Vamp1, Vamp2 and Snap25 (synaptosomal-associated protein 25)." (PMID 30001398, 2018). "The 26 bp intergenic polymorphism of VAMP2, a key component of SNARE complex, as well as its mRNA and protein levels are associated with neurological diseases." (PMID 35360211, 2022). "The LHN of BoNT/X cleaves VAMP-2 and VAMP-4 in cultured neurons and a sortase ligated BoNT/X induces flaccid paralysis in mice at μg dosage, so it could naturally be associated with neurological diseases, although this has not been demonstrated so far13." (PMID 30940836, 2019).
infection (4 papers, 2018 to 2025). The state of being infected such as from the introduction of a foreign agent such as serum, vaccine, antigenic substance or organism. "induces phagocytotic entry into the host cells by using VAMP8 at the entry site; recruits VAMP2, VAMP3, and VAMP4 on to the Salmonella-containing vacuoles during infection; and uses VAMP7 for secretion of typhoid toxins outside the host cell." (PMID 39950824, 2025). "Lentiviral infection of TeNT efficiently cleaved endogenous VAMP2 but not TI-VAMP2, which was expressed at a similar level as endogenous VAMP2." (PMID 32616842, 2020).
myopathies (1 paper, 2013). "Analysis of regenerating muscle fibers in patients with four different human myopathies revealed that levels of CHC22, GLUT4 and VAMP2 are elevated during regeneration." (PMID 24204966, 2013).
VAMP2 also shares sentences with these, for which no sentence is quoted: Rett syndrome (3 papers); Anxiety (2); autism (2); COVID-19 (2); melanoma (2); movement disorder (2); multiple sclerosis (2); Ataxia (1); attention deficit-hyperactivity disorder (1); autism spectrum disorder (1); basophilic leukemia (1); behavioral disorders (1); bipolar depression (1); Burkitt lymphoma (1); Cirrhosis (1); colon cancers (1); Creutzfeldt-Jakob’s disease (1); frontotemporal dementia (1); Hepatitis (1); Hypotonia (1); Lewy body dementia (1); Macrocephaly (1); microcephaly (1); mood disorder (1); neurodegenerative disease (1); osteoporosis (1); pancreatic adenocarcinoma (1); pancreatitis (1); Parkinson’s (1); pheochromocytoma (1).
A further 4 diseases each share a sentence with VAMP2 in 1 paper.